CA9 (carbonic anhydrase 9)
Diseases named in the same sentence as CA9 in open-access papers (continued):
Sharing a sentence is not in itself a finding about the gene and the disease.
tumor (continued). "Our results show a significantly higher mRNA expression of the hypoxia marker CA9 and SERPINE1 in all tumor biopsies (responders and non-responders) compared to normal tissue." (PMID 38016355, 2024). "The tumor cells were immunoreactive for pan-keratin (AE1/AE3) and PAX8, but no reactivity with KRT7, CA9 and TFE3." (PMID 37415400, 2024). "After carefully reviewing the histologic morphology in our present case, we have found ~10% of tumor cells showing clear cytoplasm, but all tumor cells stained consistently for S100, alpha-inhibin, NSE, Vimentin, and negative for CD10 and CA9." (PMID 35220972, 2022). "The IHC data revealed that the expression of VEGFA, CA9, and DERL3 in CC specimens was more obvious as opposed to that in normal samples, while the expression of RNF130 was decreased in tumor tissues." (PMID 35935576, 2022). "While normal pancreatic tissues showed no detectable CA9 signal, ~25% of KPC tumor tissues were hypoxic." (PMID 35626052, 2022). "The tumor cells were negative for epithelial membrane antigen (EMA), carbonic anhydrase 9 (CA9), CD10, KRT7, CD117, p504s, synaptophysin, chromogranin, melanin A, HMB45 and steroidogenic factor 1 (SF-1)." (PMID 35220972, 2022). "Although VEGF inhibitor increased tumor hypoxia in A549 and NCI-H1975 xenograft models, there are only 4 to 6% of total CA9+ cells that were CD47+, demonstrating that hypoxia was not the major cause of CD47 upregulation during anti-angiogenic therapy." (PMID 31829270, 2019). "In contrast, the expression of CA9 protein (no available mRNA data) is prevented in HT1080 and FaDu tumor cells at 0.55 mM glucose." (PMID 21306648, 2011). "Immunohistochemistry of these tumours demonstrated Avastin-induced necrosis, expression of HIF1α and the HIF target genes CA9 and VEGF (data not shown)." (PMID 20436681, 2010). "The tumour cells were also positive for GATA3, E-cadherin, Pax-8, Succinate dehydrogenase B (SDHB) and Fumarate hydratase (FH), and negative for vimentin, Carbonic anhydrase 9 (CA9), CD10, P504s, CK20, TFE3, TFEB, HMB45, ALK and Forkhead box protein I1 (FOXI1)." (PMID 36816543, 2023). "However, the expression of CA9 and CA12 is not universal across tumor types or individual patients, and until now, the major focus has been only their roles in regulating cancer cell survival." (PMID 35362480, 2022). "Similarly, exclusively stromal (and not epithelial) expression of CA9 was an indicator of a poorer prognosis in both BNIP3 methylated and unmethylated tumours (P=0.0495 and P=0.0725, respectively)." (PMID 18728663, 2008). "All the five tumours in this study had a typical immunophenotype characterized by diffuse positivity for CK7 and negativity for CD117, and were also positive for PAX-8, E-cadherin, FH and SDHB, but negative for vimentin, CD10, P504s, CA9, CK20, TFE3, TFEB, HMB45, and ALK." (PMID 36816543, 2023). "Additionally, APE1/Ref-1 knockdown inhibited 3D tumor spheroid growth significantly more than CA9 knockdown, which suggests that inhibition of CA9 alone may not be as efficient at attenuating PDAC tumor growth as dual-targeting these enzymes." (PMID 30214007, 2018). "However, concentrations below these IC50s were identified for each drug that affected tumor cell growth/survival without significant killing in the CAFs and are used in subsequent combination experiments involving dual inhibition of APE1/Ref-1 and CA9." (PMID 30214007, 2018). "Immunohistochemically, the tumor cells showed strong cytoplasmic expression for CK7, S-100, vimentin, EMA, nuclear expression for SOX10, focal membranous for CA9, and were negative for thyroglobulin, actin, calponin, PAX8, CD10, CK20, CDX2, CD117, DOG-1 and SMA." (PMID 29041930, 2017).
cancer (726 papers, 2003 to 2026). A tumor composed of atypical neoplastic, often pleomorphic cells that invade other tissues. "This was linked to decreased expression of CA9, a critical protein for pH regulation also associated with cancer progression and metastasis." (PMID 40255615, 2025). "Carbonic Anhydrase IX (CA9) is a hypoxia-inducible gene that has been associated with poor outcome in several cancers." (PMID 40723287, 2025). "Next top acetaminophen targets interacting with cancer-related genes indicated by bioinformatic analysis are CA9—a gene encoding carbonic anhydrase IX, which is a transmembrane protein catalyzing the reversible hydration of carbon dioxide." (PMID 41516250, 2025). "The key protein carbonic anhydrase 9 (CAIX), a membrane-spanning tumor-associated cell surface glycoprotein that is induced by hypoxia is involved in adaptation to acidosis and in cancer progression." (PMID 40535577, 2025). "In both heterospheroids, CA9 immunofluorescence staining was primarily associated with the cancer cells, but also some of the fibroblasts were CA9 positive." (PMID 39011470, 2024). "Carbonic anhydrase 9 (CA9) is a transmembrane protein that is often found to be associated with aggressive cancers." (PMID 35625561, 2022). "In particular, CA9 expression has been strongly associated with cancer aggressiveness and H+ fluxes versus the extracellular space, especially under hypoxia." (PMID 34124067, 2021). "Previous studies have revealed that CA9 expression is associated with poor clinical outcomes in various cancers." (PMID 32365566, 2020). "CA9 expression significantly correlated with the regulation of cell differentiation, various oncogenes and cancer‐associated pathways." (PMID 32299152, 2020). "ERO1α can serve as a novel endogenous chronic hypoxia marker that is more reliable than CA9 and can be used as a diagnostic biomarker and therapeutic target for cancer." (PMID 31142270, 2019). "The HIF1A-inducible gene CA9, which encodes carbonic anhydrase IX and regulates cellular pH to promote cancer cell survival was induced in all PTX-residual cells, and its upregulation was sustained in MDA-MB-231, SUM159T, BT549 and HCC1937 PTXR cells." (PMID 28187446, 2017). "CA9 catalyzes the reversible metabolism of carbon dioxide to carbonic acid and has been linked to malignant transformation and hypoxia in various cancers." (PMID 27478411, 2016). "The carbonic anhydrase IX (CA9) is a transmembrane enzyme implicated in development that has also been associated with cancer in multiple organs including the brain." (PMID 23889843, 2013). "Research has linked CA9 with the process of ferroptosis, suggesting it could counteract this iron-dependent form of cell death in various cancers by modifying transferrin endocytosis and stabilizing ferritin levels." (PMID 39351146, 2024). "CA9 expression in dysplasia is moderately associated with the risk for malignization." (PMID 37190121, 2023). "In conclusion, our findings demonstrate an association of a CA9 SNP, rs2071676, with cancer differentiation and invasiveness in tumors of the colon, highlighting an anatomical site-specific effect of CA9 gene polymorphisms on the progression of colorectal malignancies." (PMID 35812185, 2022). "Furthermore, the cancer cells maintain their phenotype and genotype (CA9 expression, presence of specific ccRCC mutations) and can grow in 3D collagen-based matrices." (PMID 35102500, 2022). "In addition, associations of CA9 SNPs with different aspects of cancer development have been reported 15-20." (PMID 35812185, 2022). "These lines of evidence suggest that CA9 SNPs may be suitable for predicting the risk and prognosis of cancers." (PMID 28667334, 2017). "However, little is known about the impacts of CA9 polymorphisms on cancer susceptibility and progression of HCC." (PMID 28667334, 2017). "CA9 is also now implicated as an important protein in the generation of cancer stem cells (CSCs)." (PMID 28055960, 2017).
cancer (continued). "Interestingly, many studies have shown that dysregulated CA9 expression is associated with poor clinical prognosis, the metastatic phenotype, and drug resistance in different cancers." (PMID 27009863, 2016). "CA9 expression is associated with poor prognosis in many human tumors, and may contribute to aggressive cancer phenotype." (PMID 24349364, 2013). "However, among the CA isozymes, CA9 is known to be induced in hypoxic conditions and has functional association with cancer." (PMID 22748168, 2012). "CA9 facilitates proton export, contributing to extracellular acidification while maintaining intracellular pH homeostasis, thereby enabling cancer cells to survive and thrive in acidic environments." (PMID 41535258, 2026). "We identified CA9 as a dysadherin target that is upregulated in malignant tumors and is positively correlated with CRC stage." (PMID 41535258, 2026). "Single-cell analysis revealed that LRGS scores were highest in cancer-associated fibroblasts (CAFs), with APOD and SERPINE1 highly expressed in PDGFRA+ CAFs and CA9+ CAFs, respectively." (PMID 42253954, 2026). "CA9 is typically expressed at low levels in normal tissues (primarily gastrointestinal tract) but highly upregulated in multiple cancers including CRC." (PMID 41567641, 2025). "Computational analyses also evidenced BA’s potent binding affinity with the primary cancer-related targets CA9, DHFR, and MMP1; molecular dynamics simulations validated the stability of these interactions." (PMID 41585891, 2025). "CA9 regulates intracellular and extracellular pH, influencing cancer cell survival and growth in acidic microenvironments." (PMID 40723287, 2025). "Genes upregulated in cancer cells from all 10 ccRCC tumors included the classical HIF target genes CA9 and VEGFA, as well as the atypical mitochondrial subunit NDUFA4L220." (PMID 39792555, 2025). "Cancer cell adaptation to hypoxia/acidosis drives progression—HNC often overexpresses carbonic anhydrase IX (CA9) to maintain alkaline intracellular pH." (PMID 41185600, 2025). "To validate the clinical relevance of CA9, we analyzed transcriptome data and clinical data of 364 patients from the Cancer Genome Atlas Liver Hepatocellular Carcinoma (TCGA‐LIHC) database." (PMID 40873634, 2025). "Specifically, CA9 is a well-known hypoxia-inducible gene that is commonly overexpressed in cancer cells." (PMID 38523788, 2024). "The signature genes were co-localized with the ccRCC-specific marker (CA9) in cancer tissues, revealing the existence of such three types of functionally heterogeneous cancer cells in the TME of ccRCC cases." (PMID 38944814, 2024). "CA9’s known primary role is to regulate cellular pH balance and to be critical for the growth of cancer cells in acidic or low-oxygen environments, which must cope with hypoxia and acidosis." (PMID 39768175, 2024). "While CA9, a family member, is upregulated by hypoxia in many cancers, and its inhibitors are used as anticancer drugs." (PMID 39393173, 2024). "CA9, a single-pass transmembrane receptor, is currently explored as a promising target for small molecule inhibitors and antibody-based cancer treatments." (PMID 38414005, 2024). "The discovery of CLEC2 interaction describes a new putative mechanism for CA9’s function in hematological cancers or circulating cancer cells (CTC)." (PMID 39768175, 2024). "USP43, USP52, JOSD1, UCHL5 and OTUB1 all reduced levels of the HIF-1α target CA9 in the secondary validation screen in two different non-cancer cell lines." (PMID 39009674, 2024). "In mouse models, CA9NS expression in cancer cells increased metastases, strongly supporting a functional difference between soluble and membrane-bound CA9." (PMID 39768175, 2024). "Out of the twelve human CAs, two membrane associated CA isoforms–CA9 and CA12 have been largely implicated in cancer development, particularly in case of solid cancers." (PMID 38530845, 2024).
cancer (continued). "Although CA9 exhibited high selectivity, its use as a cancer drug was constrained by its instability." (PMID 39600365, 2024). "CA9, upregulated in hypoxic conditions and overexpressed in various cancers, contributes to acidic environments and cancer cell migration and invasion." (PMID 39768175, 2024). "CA9 has been shown to be upregulated at both mRNA level and protein level in hypoxic tumors and correlates with poor prognosis in various types of cancer." (PMID 38016355, 2024). "Evidence has shown that carbonic anhydrase 9 (CA9), a glycoprotein of the zinc-containing enzyme family, was an inducible expressed gene in response to hypoxia in cancers." (PMID 38561760, 2024). "We identified the binding of CA9, a gene strongly expressed in response to hypoxia in cancer, to platelets." (PMID 39768175, 2024). "CA2 displayed an opposite expression trend to CA9, warranting further investigation of its role in cancer." (PMID 39393173, 2024). "The opposite was observed for CA9 as CA9-expression increased in cancer tissue when compared to healthy tissue." (PMID 36982873, 2023). "Hypoxic cancer cells counteract local acidosis by HIF-dependent induction of the membrane-bound ectoenzyme carbonic anhydrase 9 (CA9), which converts H2O and metabolically generated CO2 to H+ and HCO3−." (PMID 37490147, 2023). "Genetic variation in the 3' untranslated region (3'UTR) of CA9 regulates the expression of CA9 and the progression of cancer, and serves as a novel determinant and target for HCC metastasis and prognosis, according to a study conducted in Taiwan." (PMID 38114977, 2023). "We also compared the proportion of ANG-positive cells among PT in juxtatumors (CD13 positive cells) and cancer cells in tumors (CA9 positive cells)." (PMID 38025776, 2023). "For instance, the CA9 (carbonic anhydrase IX) that should be expressed only in ccRCC was found by us to be expressed not only in the cancer nodules (AVE(PTA) = 2.11, AVE(PTB) = 0.27, AVE(CWM) = 2.65) but also in the NOR (AVE(NOR) = 2.76)." (PMID 38132440, 2023). "CA9 has been reported to exert important functions in stabilizing the intracellular pH of cancer cells." (PMID 36760347, 2023). "Many of the genes upregulated, i.e., MMP1, MMP13, S100A7, CEMIP, and CA9 are known to increase in various cancer cells." (PMID 36766731, 2023). "In tumoral samples, angiogenin signal mostly colocalized with CA9 staining, used here as a marker of cancer cells." (PMID 38025776, 2023). "In general, CA9 expression increases with severity of the dysplasia and is highest in carcinoma in situs." (PMID 37190121, 2023). "It is possible that lEVs from cancer patients generate a pre-metastatic niche with a few Ca9-expressing cancer cells and stromal cells with a cancerous phenotype over expressing MMP2." (PMID 36975533, 2023). "As an adaptive response to hypoxia, the upregulation of CA9 in tumors significantly contributes to the malignant transformation of cancer and precancerous lesions." (PMID 38114977, 2023). "In summary, the activity of MCT4, NHE1, and CA9 leads to intracellular alkalization of cancer cells." (PMID 37490147, 2023). "Here, we attempted to interrogate the effect of CA9 gene polymorphisms on the development of CRC in 470 cases and 470 gender- and age-matched non-cancer controls." (PMID 35812185, 2022). "Previous studies observed that genes such as CA9, CKB and GLIPR2 were strongly associated with the prognosis of cancer." (PMID 36341424, 2022). "Controlling CA9, which is induced under hypoxic conditions, is critical for improving the outcomes of cancer therapy." (PMID 36415514, 2022). "In general, CA9 expression is suppressed in normoxia, but highly upregulated by hypoxia in a variety of cancer cell types." (PMID 35328229, 2022).
cancer (continued). "A latest research showed that the expression of early growth response 1 (EGR1) and its downstream target carbonic anhydrase 9 (CA9), which were up-regulated in hypoxic cancers, are significantly increased in ectopic lesions." (PMID 36339404, 2022). "CA9, as a member of the CAs family, has become a biomarker for the therapy of a wide range of cancers." (PMID 36467089, 2022). "Repeated analysis in second human cancer cell line, A549, uncovers cell type specific responses, with 2 out the 6 sites studied (CA9 and FGF11 promoters) only displaying accessibility sensitivity to hypoxia in HeLa cells." (PMID 35258521, 2022). "Carbonic anhydrase 9 (CA9) is a cell-surface pH modulator that has been demonstrated to contribute to key steps of cancer progression." (PMID 35812185, 2022). "The proliferation and invasion ability of cancer cells transfected with ZCCHC14 CRISPR/Ca9 KO plasmids was significantly enhanced (P < .05)." (PMID 33345444, 2021). "The expression pattern of CA9 is significantly different from other CA family members: CA9 can only be found in a few normal tissues, but its abnormal expression is closely related to many cancer types." (PMID 35155218, 2021). "As proof of concept, we targeted three transmembrane proteins linked to cancer, tetraspanin CD151, carbonic anhydrase 9, and integrin-α11." (PMID 33980972, 2021). "We performed intersection analysis between NACDGs and found that CYBB and CA9 are shared among all cancer datasets." (PMID 33670487, 2021). "In summary, we show that the well-established histological features of ccRCC, including lipid deposition and elevated expression of key cancer biomarkers (i.e., CA9 and ENO1), are significantly decreased with Ndufa4l2 knockdown in our TANdu mouse model." (PMID 34970493, 2021). "Recent studies indicated that the hypoxic condition of the cancer microenvironment regulates the expression CA9." (PMID 32299152, 2020). "The glycoprotein CA9 has been studied in the recent years, whereby the expression was higher in wide spectrum of malignancy and showed the potential for cancer therapy." (PMID 32365566, 2020). "In sinonasal papilloma, CA9 expression correlated with cancer cells differentiation and proliferation and emerged as a marker of cancer recurrence." (PMID 32299152, 2020). "Meanwhile, high CA9 levels reduce the chemosensitivity and facilitate the survival of various cancer cells by enhancing the acidification of the cancer microenvironment." (PMID 32299152, 2020). "CA9 is a member of the carbonic anhydrases’ family, that is often expressed in cancer cells under hypoxic condition." (PMID 32299152, 2020). "This was significantly higher in the stroma-adjacent cancer cell areas with strong CA9 expression (median value 20% vs. 5%, mean value 22.3% vs. 9.2%, p < 0.00001)." (PMID 32066909, 2020). "Membrane expression of CA9 was noted in a varying percentage of cancer cells, ranging from 0 to 90% (median 5%, mean 16.7%)." (PMID 32066909, 2020). "CA9 is a member of the carbonic anhydrases family, that is often expressed in cancer cells and under hypoxic conditions." (PMID 32299152, 2020). "The significant increase in cancer cell CA9 expression at 1% O2 validates the cellular sensing of the hypoxic stimulus, to which both cells were simultaneously exposed to, without affecting cellular viability between the conditions." (PMID 32231135, 2020). "Previous studies have reported that CA9, EXTL2, PGAM1, and TYMS were dysregulated across multiple human cancers and intricately associated with tumorigenesis by functioning as key enzymes underlying metabolism." (PMID 33425725, 2020). "JMJD2B has been shown to play a role in altering the expression of many cancer associated genes including cyclin-dependent kinase 6 (CDK6), and carbonic anhydrase 9 (CA9), which can directly affect the transmembrane pH gradient." (PMID 32292719, 2020).